RNU6-1007P (RNA, U6 small nuclear 1007, pseudogene)
Gene: Small nuclear RNA gene on chromosome 2 (88,414,898 to 88,415,004, reverse strand). Ensembl gene ENSG00000252395.
Homologues: Orthologues: chimpanzee U6 (95% identical), macaque U6 (90% identical). Paralogues in human: RNU6-116P (89% identical), RNU6-25P (88% identical), RNU6-33P (88% identical), RNU6-348P (88% identical), RNU6-41P (88% identical), RNU6-698P (88% identical), RNU6-1 (87% identical), RNU6-1060P (87% identical), RNU6-15P (87% identical), RNU6-19P (87% identical), RNU6-2 (87% identical), RNU6-20P (87% identical), and 1286 more.